BCL9L (BCL9 like)
Diseases named in the same sentence as BCL9L in open-access papers (continued):
Sharing a sentence is not in itself a finding about the gene and the disease.
tumor (continued). "Here, we report that inhibition or depletion of BCL9/BCL9L markedly restrained tumor growth and enhanced antitumor responses." (PMID 38811552, 2024). "Upregulation of BCL9L activates Wnt/β-catenin signals and finally increases the stemness of tumor cells." (PMID 36918563, 2023). "BCL9/BCL9L inhibited the infiltration of CD8 + T cells in the tumor microenvironment, and promoted striple-negative breast cancer growth through the Wnt and TGF-βpathways." (PMID 37013637, 2023). "Targeting BCL9/BCL9L shows a direct anti-tumor effect, which involves anti-tumor immune responses through inhibiting Wnt and TGF-β signal transduction." (PMID 36918563, 2023). "This study showed for the first time that BCL9L is overexpressed in dysplastic urothelial cells and MIBC, suggesting an association with tumour stage and invasiveness." (PMID 35628130, 2022). "Based on the analysis of our data, BCL9L expression was positively correlated with tumour invasiveness (tumour stage), metastatic ability (lymph node metastasis), cellular pleomorphism (tumour grade) and tumour progression (clinical stage)." (PMID 35522942, 2022). "Clonal status of BCL9L mutation are significantly associated with MSI status, tumour site, AJCC stage, N stage and M stage." (PMID 35962343, 2022). "The mechanism of action of BCL9L is mostly based on the enhancement of the canonical Wnt/β-catenin signalling in order to further contribute to tumour progression." (PMID 35628130, 2022). "The impairment of β-catenin binding to Bcl9/Bcl9L also significantly reduced tumor progression and lung metastasis formation." (PMID 34545187, 2021). "Here, we have analyzed the effect of interfering with the Bcl9/Bcl9L branch of Wnt signaling on tumor cell growth and invasion in a mouse model of metastatic breast cancer (FVB/N-Tg(MMTV-PyVT)634Mul/J)." (PMID 34545187, 2021). "Here, we have dissected the roles of the interactions of Bcl9 and Bcl9L with Pygopus and with β-catenin during tumor progression and metastasis formation in the MMTV-PyMT mouse model of metastatic breast cancer." (PMID 34545187, 2021). "The Wnt signaling protein BCL9L is upregulated in soft tumor cells and regulates their stemness and tumorigenicity." (PMID 33274785, 2021). "To confirm the involvement of BCL9L in matrix stiffness-induced tumor stemness, we knocked down BCL9L in LN229/T98G cells using short hairpin RNA (shRNA) technology and overexpressed BCL9L in LN229/T98G cells." (PMID 33535177, 2021). "To further validate these in vitro results in vivo, we inoculated mice with 100 soft SGGFP‐ or BCL9L‐SGs‐tumor cells." (PMID 33274785, 2021). "In line with this upregulation of BCL9L, the expression of the total β‐catenin and its nuclear form was also enhanced in the soft tumor cells and an enhanced nuclear translocation was observed (and EV5C and D)." (PMID 33274785, 2021). "An important finding in this study is that BCL9L is identified as a biological marker for soft tumor cells to distinguish them from their stiff counterparts." (PMID 33274785, 2021). "Bcl9/Bcl9L contribute to the initiation and maintenance of TGFβ-induced EMT and cell migration in vitro, yet the complete loss of Bcl9/Bcl9L has led to tumor cell apoptosis in vitro and in vivo." (PMID 34545187, 2021). "To further confirm the role of BCL9L in ITBG1 induced tumor progression, we silenced BCL9L in SGC-7901 and BGC-823 cells." (PMID 34319913, 2021). "In line with this in vivo result, BCL9L knockout also inhibited soft tumor cell invasion in vitro (Fig EV5I)." (PMID 33274785, 2021). "In summary, miR-766-3p, a negative regulator of BCL9L, plays the role of tumor metastasis suppressor via the β-catenin signaling pathway in the progression of OS." (PMID 33117820, 2020). "BCL9L promotes tumor growth and local invasion in mouse intestinal tumors by increasing the expression of canonical Wnt target genes." (PMID 31440992, 2020).
tumor (continued). "In support of our in vitro data, results from in vivo xenograft experiments showed reduced tumor growth of BCL9L knockdown cells." (PMID 27713160, 2016). "We observed a significant reduction of tumor weight by 50% in mice harboring BCL9L knockdown xenografts compared to controls." (PMID 27713160, 2016). "Second, we were unable to compare the prognostic impact of MATH and BCL9L mutational status with that of established clinicopathological markers, such as primary tumor sidedness, which was not collected for this cohort." (PMID 41051593, 2025). "In summary, our data uncover that targeting BCL9/BCL9L plays a key role in cDC1-regulated presentation of tumor-derived antigens and subsequently in cDC1-triggered activation and tumor infiltration of CD8+ T cells, constituting a positive feedback loop required for optimal antitumor immunity." (PMID 38811552, 2024). "In addition, the localisation of BCL9L was observed to be both in the nucleus and cytoplasm of tumour cells but with stronger staining in the nucleus, in agreement with its role as transcriptional cofactor of Wnt/β-catenin." (PMID 35628130, 2022). "Importantly, we found that knockdown of BCL9L impaired tumour formation in both cell types, further indicating that BCL9L is an ∆Np63-regulated oncogene." (PMID 35105868, 2022). "Our study further demonstrated that type I collagen could mediate the activation of ITGB1/BCL9L/β-catenin signaling pathway, leading to the tumor progression and drugs resistance." (PMID 34319913, 2021). "We found that BCL9L levels were much higher in soft tumor cells compared with stiff ones." (PMID 33274785, 2021). "In contrast, disrupting the interaction of Bcl9/Bcl9L with β-catenin, either by deletion of their HD2 domains or by a point mutation in the N-terminal domain of β-catenin (D164A), diminished primary tumor growth and tumor cell proliferation and reduced tumor cell invasion and lung metastasis." (PMID 34545187, 2021). "Conditional knockout of both Bcl9 and Bcl9L resulted into tumor cell death." (PMID 34545187, 2021). "In tumor xenograft formation assay, we found that miR-424-5p overexpression or silencing BCL9L alone slightly suppressed tumor formation of HuCCT1-Gem cells, but dramatically increased gemcitabine sensitivity and reduced tumor growth when treated with gemcitabine." (PMID 33436545, 2021). "Motivated by this and the knowledge of a functional requirement of Bcl9 and Bcl9L for EMT in MMVT-PyMT-derived tumor cell lines in vitro, we next studied the expression of both proteins during the different stages of tumor progression in mammary glands of MMTV-PyMT transgenic mice in vivo." (PMID 34545187, 2021). "BCL9L is upregulated in soft tumor cells but very weakly expressed in stiff tumor cells." (PMID 33274785, 2021). "Consistently, elevated expression of BCL9L was observed in tumor tissues from CR patients." (PMID 34319913, 2021). "BCL9L expression in 60 paired OS and peritumor tissues was measured by qRT-PCR and Western blotting, and the expression level of BCL9L was significantly more in tumor than in peritumor tissues (P < 0.05)." (PMID 33117820, 2020). "Taken together, these results suggest a haploinsufficient model of tumor suppression for BCL9L." (PMID 28073006, 2017). "Moreover, the intensity of BCL9L staining in PDAC tissue samples significantly correlated with differentiation grade of the tumor." (PMID 27713160, 2016). "Overall the expression of BCL9L nevertheless correlated with the aggressiveness of the tumor." (PMID 27539223, 2016). "Also, the BCL9L knockout abrogated the lung metastasis of soft tumor cells (and EV5H)." (PMID 33274785, 2021). "Immunohistochemical staining also revealed that Bcl9 and Bcl9L proteins were both still expressed in cytosols and nuclei of tumor cells of MCre+ genotype, suggesting either a low recombination efficiency or a competitive selection against recombined tumor cells." (PMID 34545187, 2021).
tumor (continued). "Importantly, these tumours were escapers that retained expression of both Bcl9 and Bcl9l." (PMID 30760720, 2019). "Across tumor cell populations, TBX3 expression significantly overlapped with that of BCL9 and BCL9L in individual cells." (PMID 40343989, 2025). "For example, the genes BCL9L or SKI—found to be up-regulated in vivo and in vitro—are potentially involved in tumor growth and initiation via modulation of the TGFβ (SKI) or WNT-β-catenin (BCL9L) pathway." (PMID 39063079, 2024). "In BLCA, NAT10 overexpression acetylates BCL9L, SOX4, and AKT1, promoting tumor invasion and metastasis." (PMID 38233930, 2024). "Our studies showed that targeting BCL9/BCL9L facilitates antigen presentation and tumor infiltration of cDC1, as well as boosts tumor infiltration of CD8+ T cells, indicating a critical role of targeting BCL9/BCL9L in overcoming immunotherapy resistance." (PMID 38811552, 2024). "For example, BCL9L, P2RX6, RER1, EFNA2, CASK, CERCAM, and PTPRN were demonstrated to promote EMT, metastasis, and invasion of tumor cells." (PMID 35586092, 2022). "In accord with the findings in vitro, the staining frequency and intensity of BCL9L, SOX4 and AKT1 decreased significantly in downregulated‐NAT10 xenograft tumours." (PMID 35522942, 2022). "IPMN, accordingly, showed intermediate expression of BCL9L, but instead demonstrated a high expression of the cyclin D1 inhibitor INPP5D, possibly contributing to the better prognosis of this neoplasia compared to PDAC." (PMID 27539223, 2016). "In addition, genes related to tumor spreading, cell migration, and cytoskeletal reorganization were also up-regulated in vitro and in vivo, such as CDC42, DNMBP, CAPG, NRAS, BCL9L, etc.." (PMID 39063079, 2024). "Overall, BCL9L was expressed very heterogeneously in tumour samples as well as in dysplastic and non-dysplastic urothelium." (PMID 35628130, 2022). "The same is found in papillary tumour formations, especially the peripheral cell layers that express BCL9L, while inner tumour layers are often weak stained or negative." (PMID 35628130, 2022). "The papillary primary non-muscle-invasive tumours expressed BCL9L very heterogeneously, predominantly in the peripheral cell layers with weak to moderate intensity, however, the average H-score was 0.63." (PMID 35628130, 2022). "In addition, we found that the expression of stemness genes was upregulated in the soft tumor cells (Nestin, OCT3/4 and SOX2 for 4T1/MCF‐7; Nanog, OCT3/4, SOX2, and CD133 for B16F1/MP‐1), while the BCL9L knockout reversed this effect (Fig EV5G)." (PMID 33274785, 2021). "Twelve weeks later, we found that the soft SGGFP‐tumor cells formed a tumor in the mice; in contrast, no tumors were formed in the BCL9L knockout group." (PMID 33274785, 2021). "In conclusion, we showed that type I collagen could mediate the tumor progression and chemotherapy though an ITGB1 based manner, which was dependent on BCL9L/β-catenin/BCL2 signaling pathway." (PMID 34319913, 2021). "However, MIBC patients 3, 5, and 8 also contain negative tumour cell areas for BCL9L, which were in the neighbourhood of moderately stained areas." (PMID 35628130, 2022). "To further validate whether there was a selection against tumor cells lacking both Bcl9 and Bcl9L, we examined whether the genetic deletion of Bcl9/Bcl9L affected tumor cell survival." (PMID 34545187, 2021).
infection (1 paper, 2021). The state of being infected such as from the introduction of a foreign agent such as serum, vaccine, antigenic substance or organism. "Floxed alleles of Bcl9, Bcl9L, and β-catenin genes were recombined by infection with Adenovirus expressing Cre-recombinase and GFP (Ad-Cre-IRES-GFP)." (PMID 34545187, 2021).
BCL9L also shares sentences with these, for which no sentence is quoted: adenoma (2 papers); invasive carcinoma (2); astrocytoma (1); blood cancer (1); breast tumors (1); choriocarcinoma (1); colitis (1); hepatitis B infections (1); invasive breast carcinoma (1); lung adenocarcinoma (1); metastatic colorectal cancer (1); oligodendroglioma (1); septic shock (1); squamous cell carcinoma (1); viral infection (1).